CXCL13 (C-X-C motif chemokine ligand 13)
Diseases named in the same sentence as CXCL13 in open-access papers (continued):
Sharing a sentence is not in itself a finding about the gene and the disease.
tumor (continued). "In pancreatic cancer, neoadjuvant chemotherapy reversed the PD‐L1/PD‐1‐mediated inhibition of Tfh cells, enabling CXCL13‐mediated recruitment of B cells and IL‐21‐driven differentiation of PCs, ultimately enhancing anti‐tumour immunity." (PMID 38997802, 2024). "NSwM B cells positively correlated with Tfh, TLS, and tumor center CD20 + B cells, but inversely correlated with BCA-1/CXCL13 and BAFF, both of which were significantly associated with poorer OS." (PMID 39014460, 2024). "Correlation between CXCL13 and tumor immune microenvironment (TIME) was evaluated using multiple algorithms." (PMID 38459390, 2024). "They found that CXCL13+PD-1+ CD4+ T cells (equal to CD4.c16/17) augmented antitumor cytotoxicity through interaction with LAMP3+ DCs in tumor-draining lymph nodes (TDLNs)." (PMID 38343549, 2024). "Across all samples, CXCL13 expression levels were consistently higher in the tumor tissues relative to the adjacent healthy tissues." (PMID 39344390, 2024). "In our study, we have discovered a significant association between improved clinical outcomes in NSCLC patients treated with immunotherapy and an increased density of CXCL13 within TLSs compared to the tumor itself." (PMID 38398098, 2024). "Tumor-specific CD4 + T cells showed higher expression levels of chemokine CXCL13, immune regulators FOS and JUN, and exhaustion markers TIGIT." (PMID 39033098, 2024). "Tfh cells induce B cells to initiate antibody responses outside follicles and germinal centers, express the chemokine CXCL13 to recruit CD8 + T cells for anti-tumor immunity, and dedicate themselves to the efficacy of anti-PD-L1 and PD-117,18." (PMID 38493212, 2024). "When mismatch repair-deficient (MMRd) and MMR-proficient (MMRp) CRC samples were compared, IFNβ expression in cluster 3 and cluster 4 CD4+ T cells (positive for CXCL13) was found to be significantly greater in the MMRd tumor samples." (PMID 38383773, 2024). "In cancer, the production of CXCL13 also marks the presence of tertiary lymphoid structures (TLSs), which are aggregates of B cells, T cells and DCs, in the tumor microenvironment." (PMID 38928238, 2024). "Further, exhausted tumor-infiltrated CD103+ CD8+ T cells express CXCL13 upon TGFβ stimulation, which can directly recruit B cells." (PMID 38786066, 2024). "In our study, we found that CXCL13 was specifically upregulated in tumor-infiltrated TCR135-positive CD4+ T cells, while ZNF683 was specifically upregulated in tumor-infiltrated TCR135-positive CD8+ T cells." (PMID 38412034, 2024). "We further compared the exhaustion scores of CD4+T cells and showed that Treg cells and CXCL13+T cells had higher exhaustion scores in obese tumor samples." (PMID 38311726, 2024). "In pancreatic ductal adenocarcinoma, the use of CXCL13 antibodies to inhibit the migration of Bregs has demonstrated promising anti-tumor effects." (PMID 39519376, 2024). "CXCL13 regulates the tumor lymphocyte infiltrate, and CXCL13 expression on CD8+ T cells has been shown to be a predictor of immune checkpoint inhibitor response." (PMID 39541169, 2024). "Noteworthily, HPV+ OPSCC tumor cells embrace extensive intercellular communications with CXCL13+CD4+ T cells." (PMID 39105803, 2024). "While CXCL13 expression was upregulated in three out of four clusters within the tumor area, it was nearly undetectable in the normal epithelium and stroma." (PMID 39344390, 2024). "Among them, CD4_C3_CXCL13 T cells emerged as the most extensive communicative with HPV+ tumor cells, especially through CD74-COPA, CD74-MIF and CD2-CD58, which play a critical role in MHC-II antigen presentation and T cell activation." (PMID 39105803, 2024). "To determine the specific immune cell populations responsible for TGFβ and CXCL13 secretion within the tumour microenvironment, we analysed immune spots using multiple methods, including spatial‐geneset‐score analysis, CIBERSORT and MCPcounter analysis." (PMID 38426403, 2024).
tumor (continued). "CXCL13 recruits B cells to the tumor region to form TLSs, and the investigators revealed that, in the tumor microenvironment, Th-CXCL13 cells clustered in the central B-cell region and formed within the follicular TLSs." (PMID 38628669, 2024). "Remarkably, the levels of serum CXCL13 were consistently elevated in patients with OSCC, and the high expression of serum CXCL13 was notably associated with tumor size and neck lymph node metastasis." (PMID 39344390, 2024). "An outlier component (not in the giant connected component) was made of the CXCL chemokine family, stemming from CXCL13—a recently recognized immune checkpoint with a key role in tumor progression." (PMID 39484215, 2024). "We identified CXCL13 as the gene exhibiting the highest covariance with tumor reactivity as well as exhaustion factors." (PMID 37735262, 2024). "In agreement with this, MMRd CRCs display strong TLS signatures and have a significant presence of CXCL13-expressing T cells throughout the tumor and CXCL13-expressing follicular DCs in TLSs." (PMID 39544936, 2024). "In female BCa, the tumor microenvironment shows significant increases in B cell recruitment via CXCL13 expression, along with higher PD-L1 expression, increased infiltration of CD163+ M2-like TAMs, and differences in immunoregulatory gene expression." (PMID 39409924, 2024). "Interaction with HPV+ OPSCC tumor cells amplifies CXCL13 and IFNγ release in CD4+T cells, fostering a pro-inflammatory TME." (PMID 39105803, 2024). "These factors contribute to the formation of HEVs, with CXCL13 attracting B cells to migrate to the tumor region and IL-21 supporting recruited B cells." (PMID 39026670, 2024). "The expression of angiogenic factors (e.g., Angiopoetinn-1, FGF acidic), chemokines (e.g., CCL2, CXCL13), and inflammatory cytokines (e.g., IL-6, IL-1 beta), which were elevated in serum from tumor embedded mice, was suppressed by Pn-21Ab administration." (PMID 39334860, 2024). "CXCL13 and IL-7 interaction recruits LTi expressing lymphotoxin- α1β2 (LT- α1β2), which binds to the LT-βR on tumor stromal cells." (PMID 38333212, 2024). "CXCL13+CD8+ T cells have been described as tumor-reactive cells triggered by immune-checkpoint blockade, but to our knowledge, this population has not previously been demonstrated to contribute to skin inflammation." (PMID 39541169, 2024). "CXCL13(C-X-C motif chemokine ligand 13) is vital for the recruitment of B cells and T follicular helper cells into the tumor microenvironment." (PMID 39687627, 2024). "Specifically, the majority of CD8+T cell clusters were significantly enriched in adjacent normal tissue samples, whereas CD4+T cell clusters including CXCL13+T cells and Treg cells showed higher enrichment in tumor samples." (PMID 38311726, 2024). "High expression of CXCL13 in Pan-Gyn correlates with a favorable clinical prognosis, increased immune cell infiltration, and reduced intra-tumor heterogeneity." (PMID 38459390, 2024). "Consistent with our results, we demonstrated that PD1+CXCL13+CD8+T cells possess superior anti-tumor abilities both in vivo and in vitro." (PMID 39493749, 2024). "Based on our results, we believe CXCL13+ cells have a propensity to migrate from NT to IM and toward TLSs in patients who have at least two TLSs in their tumor area and have different functions in those different locations." (PMID 38398098, 2024). "Our findings provide insights into the distribution and specific localization of CXCL13+ cells within different areas of NSCLC patients’ tumor sites, including the IM, TLS, and NT regions." (PMID 38398098, 2024). "Given that CXCL13 exhibits both pro- and anti-tumor properties, further research is needed to elucidate its role in various cancers and to define its potential therapeutic applications." (PMID 39409924, 2024). "In contrast, endoscopic recombinant CXCL13 injection within the colonic submucosa of wild-type mice inhibited tumor growth in wild-type mice." (PMID 39001456, 2024).
tumor (continued). "The accumulated Tfh and CXCL13 levels in tumor tissues are directly related to TLS in tumor tissues and can be used as biomarkers to predict progression‐free survival." (PMID 38469550, 2024). "CXCL13+ cancer-associated fibroblasts promote B cell adhesion and antibody production, activating CXCL13+CD8+ T cells that become exhausted in tumour cell aggregates." (PMID 39231979, 2024). "IHC staining for CXCL13 was carried out on a representative slide from a resection specimen, and CXCL13+ cell density was evaluated in tumor (T), invasive margin (IM), non-tumor (NT), and tertiary lymphoid structure (TLS) compartments." (PMID 38398098, 2024). "The presence of CXCL13 in the tumor environment has been suggested to influence cancer cell proliferation and migration." (PMID 39344390, 2024). "CXCL13, which is a well-recognized tumor-specific T-cell marker was elevated in proliferating CD8+ T cells." (PMID 39431011, 2024). "Production of CXCL13 by T follicular helper (Tfh) cells is essential for tertiary lymphoid structure (TLS) formation at tumor sites as well as germinal center B-cell activation, which has been linked with antitumoral response to ICB." (PMID 38722600, 2024). "Previous reports suggested that PD-1+ tumour-infiltrating lymphocytes exhibit high expression of CXCL13." (PMID 37735150, 2023). "The presence of CXCL13 in the 4T-1 tumor microenvironment facilitated the immune response and passively correlated with higher overall survival (OS) in patients with BC." (PMID 37370814, 2023). "Our findings indicated that as the TNM staging of the cancer progressed, meaning the cancer became more advanced, and as the tumor differentiation worsened, meaning the cancer cells were becoming more abnormal, the expression level of CXCL13 increased." (PMID 37025603, 2023). "Immunocompetent mouse recombinant CXCL13 showed a significantly increased area of TLSs per tumor area, increased infiltration of CD8+ T cells around TLSs, and prolonged survival time compared with the control group." (PMID 38023214, 2023). "Within the tumor microenvironment, CXCL13 is secreted by multiple populations of cells, including lymphocytes, endothelial cells, stromal cells, and tumor cells." (PMID 37958571, 2023). "Regardless, the finding that CD4+ CTLs are predisposed to invoke B cells and mediate humoral immunity through CXCL13 expression emphasizes their central role in tumor immunity in addition to their CD8+ CTL counterparts." (PMID 38077321, 2023). "The expression of CXCL13 can also be epigenetically tuned by the combined application of the HDACi entinostat with tumor-targeted delivery of interleukin-12 (IL-12), which achieved an elevated level of CXCL13 and CXCL9." (PMID 38044445, 2023). "The presence of tumour-infiltrating CXCL13+ T cells is the best predictor of responsiveness to anti-PD-1/anti-PDL1 efficacy." (PMID 37520560, 2023). "The sensitivity and specificity of CXCL13 were 60% and 80%, respectively, which means that 60% of the lung tumor cases were correctly identified, and 80% of the non-tumor cases were correctly identified." (PMID 37025603, 2023). "It has been reported that CXCL13 produces an anti-tumor immune response in BC by regulating immune activity." (PMID 37332770, 2023). "Tumour-reactive T cells producing the B-cell attractant chemokine CXCL13, in solid tumours, promote development of tertiary lymphoid structures (TLS) and are associated with improved prognosis and responsiveness to checkpoint immunotherapy." (PMID 37520560, 2023). "In bladder cancer, CXCL13 expression can be used as a surrogate marker for tumor TLSs and correlates with the response to immune checkpoint inhibitors (ICIs) in patients." (PMID 37342327, 2023). "The PRF1 cluster also upregulated Th1 markers IFNG and CXCL13, which contribute to tumor control by up-regulating HLA-II and promoting the formation of tertiary lymphoid structures (TLS), respectively." (PMID 37185301, 2023).
tumor (continued). "Fascinatingly, CXCL13’s primary expression was observed in NK cells, and this expression was elevated in NK cells within tumor tissues, particularly in carcinomas." (PMID 38023180, 2023). "Fibroblasts from tumours express higher levels of CXCL13, BAFF, and APRIL and are dependent on the CXCR5-CXCL13 axis to promote the accumulation of B cells in tumours and increase the proliferation of fibroblasts and TLS expansion in the TME." (PMID 36890557, 2023). "CAF and TGFβ inhibition also reduces the expression of Th2 cytokine and chemokine CXCL13, decreases myeloid-derived suppressor cells, Tregs, and M2 macrophages in the tumor area, and decreases tumor growth and metastasis to the lungs." (PMID 37046676, 2023). "A high concentration of lymphocytes and dendritic cells, as well as genetic TME markers such as MUC-1 and CXCL13 in the residual tumor, are valuable prognostic factors of survival and relapse in TNBC patients." (PMID 36765559, 2023). "The CD8-Tterm.ex upregulated CXCL13, a chemokine found to be overexpressed by tumor-reactive T cells in various cancer types." (PMID 37655659, 2023). "It is worth noting that our analysis of COAD bulkRNA-seq data in a previous study indicated downregulated CXCL13 in tumor samples." (PMID 38023180, 2023). "The third most frequently implicated hallmark (14 proteins) was “tumor-promoting inflammation”, including markers such as CXCL9, CXCL13, CXL17, IL6, and IL2-RA." (PMID 37264016, 2023). "In ICI OT-R tumors, the increase of TLS-associated CXCR5+ B and Tfh cells were correlated with increased mRNA expression of CXCR5’s ligand, CXCL13, by activated, tumor reactive CXCL13+ CD8 T cells." (PMID 37435085, 2023). "This review summarizes our current understanding of the CXCR5/CXCL13 immune axis, its role in TLS formation within cancer tissue and the associated tumor microenvironment (TME), and its influence on anti-tumor immune defenses." (PMID 36836910, 2023). "published the spatial single- cell immunophenotyping of the tumor microenvironment of 27 NSCLC patients following ICI and found that CXCL13 expression on CD4+ T-cells was associated with good prognosis." (PMID 37901220, 2023). "In humans, an IFNγ-induced signature, including CXCL9/CXCL13 expression, was associated with a favorable response to ICB in multiple tumor types." (PMID 37492581, 2023). "The idea that the upregulation of CXCL13 is a consequence of an immune‐suppressed tumor microenvironment was also shown by our results." (PMID 36453453, 2023). "A recent study demonstrated that CXCL13 contributes to tumor metastasis by affecting the recruitment of regulatory B cells." (PMID 37958571, 2023). "CXCL13, also known as B Cell-Attracting chemokine 1 (BCA-1), is a chemokine involved in anti-tumor immune response and B-cell attraction in germinal centers." (PMID 36765559, 2023). "Of note, CXCL13+ PD1+ TOX+ CD8 T cell population was recently reported to comprise a high fraction of tumor antigen-specific CD8 T cells." (PMID 37435085, 2023). "The discrepancy is likely due to the secretion of CXCL13 protein in tumor-specific CTLs upon TCR stimulation." (PMID 37185301, 2023). "It has been affirmed that TFH cells recruited CD8 T cells and B cells by secreting CXCL13 and facilitated the maturation of B cells into antibody-producing plasmocytes by secreting interleukin 21 (IL-21), thereby affecting tumor microenvironment." (PMID 37371833, 2023). "Recently, another study found that pre-treatment levels of tumor infiltrating CXCL13 + exhausted CD8 + T cells were predictive of response to paclitaxel combined with atezolizumab in TNBC patients." (PMID 37294342, 2023). "Tumors harboring exhausted-like T cells show increased expression of MHC-I on tumor cells and of CXCL13 on T cells, as well as altered spatial organization with more immature rather than mature tertiary lymphoid structures." (PMID 36609566, 2023).
tumor (continued). "Circulating melan-A/MART-1 reactive T cells had a greater capacity for IFN-γ production while tumour-infiltrating cells produced more CXCL13 and displayed higher expression of co-inhibitory molecules." (PMID 37520560, 2023). "The chemokine CXCL13 is known to influence local anti‐tumor immunity by recruiting immune cells and forming tertiary lymphoid structures (TLS)." (PMID 36453453, 2023). "We also found that abnormal expression of CXCL9 (P = 0.0201), CXCL11 (P = 0.0385), and CXCL13 (P = 0.0288) was closely associated to tumor stage, and the expression of CXCL9, CXCL11, and CXCL13 decreased with the increase of stage." (PMID 36798787, 2023). "Nevertheless, several studies have reported CXCL13-producing CD4+ T cells, which have been associated with favorable outcomes of tumor immunity." (PMID 38077321, 2023). "Two lines of evidence indicate environmental factors in the TME promote CXCL13-production in tumour reactive T cells." (PMID 37520560, 2023). "This illustrates the importance of CXCL13-producing T cells as an indicator of pre-existing anti-tumour immunity with the potential for amplification during successful immunotherapy." (PMID 37520560, 2023). "The CXCL13/CXCR5 axis is crucial for intra-tumor T-cell migration, and accordingly, tumors with high CXCL13 expression exhibit an increased infiltration of activated CD8+ CXCR5+ T cells." (PMID 37898752, 2023). "Several studies have shown CXCL13+ T cells are tumour reactive and co-expression of CD39 and CXCL13 allows effective enrichment of tumour reactive CD4+ T cells in NSCLC." (PMID 37520560, 2023). "The results of comparing the normal samples and the tumor samples showed that CXCL13 was significantly upregulated in tumor samples (p < 0.001) and positively correlated to major cytolytic activity‐related genes." (PMID 36453453, 2023). "CAF stimulate expression of multiple co-inhibitory markers when present during T cell activation including high levels of PD-1 expression and upregulation of CD39, features found in tumour infiltrating CXCL13 producing T cells." (PMID 37520560, 2023). "Another interesting finding was that CD4+ CTLs expressed B cell-attracting chemokine CXCL13, thereby inducing B cell migration to tumor lesions." (PMID 38077321, 2023). "Experimentally, the relationship between CXCL13 and checkpoint inhibition was established in a recent study showing that peri-tumoral administration of recombinant CXCL13 synergises with anti-PD-1 treatment to decrease tumour growth." (PMID 37520560, 2023). "We detected ex-vivo CXCL13 production mainly in CD8+ T cells from the tumor site, significantly highest in PD1+CD28− TRM." (PMID 37898752, 2023). "It is widely recognized that immune effector cells expressing PD-1 migrate from the blood to the sites of immune priming in secondary lymphoid organs or tumor microenvironment via CXCR5/CXCL13, in which they become resident cells." (PMID 37691941, 2023). "In univariable analysis, ECOG (p < 0.0001), CD8 (p = 0.036), and CXCL13 in tumor cells (p < 0.0001) were critical prognostic markers for disease progression after treatment in PDAC." (PMID 36650632, 2023). "In patients treated with ICB, high CXCL13 expression leads to more favorable tumor outcomes perhaps due to CXCR5+CD8 T cells expanding the effector T cell pool or as a consequence of these cells increasing proliferation while resisting apoptosis." (PMID 36314014, 2022). "GLDC is also close to rs55933544 and positively expressed in tumour cells, CD4_C4_CXCL13 cells, B cells and ECs." (PMID 36305631, 2022). "A subsequent study identified c-Myc activation to be involved in CXCL13-mediated upregulation of RANKL in tumor bone marrow environment in the OSCC." (PMID 36217194, 2022). "Previous studies have indicated that the prognostic role of CXCL13 seems to be tumor-type dependent." (PMID 35570844, 2022).